FRMPD1 (FERM and PDZ domain containing 1)
Description:
Stabilizes membrane-bound GPSM1, and thereby promotes its interaction with GNAI1.
Synonyms: FRMD2; KIAA0967
Tractability: Antibody: UniProt places it where antibodies can reach, with high confidence; its Gene Ontology location is reachable by antibodies, with high confidence.
Gene: Protein-coding gene on chromosome 9 (37,650,954 to 37,746,904, forward strand). Ensembl gene ENSG00000070601.
Subcellular location: Cytoplasm, cytosol; Cell membrane
Gene Ontology:
Molecular function: protein binding
Biological process: establishment of protein localization to membrane; regulation of G protein-coupled receptor signaling pathway; establishment of protein localization
Cellular component: cell cortex; plasma membrane; protein-containing complex; cytosol
Genetic constraint (gnomAD): Loss-of-function variants: 53 observed, 88.56 expected, observed/expected ratio (o/e) 0.6, 90% interval 0.48 to 0.75. The upper end of that interval is the gene's LOEUF score, 0.75, which puts it in group 3 of 6, group 1 being the genes least tolerant of losing a copy. Missense variants: 1,578 observed, 1,826.5 expected, observed/expected ratio (o/e) 0.86, 90% interval 0.83 to 0.9. Synonymous variants: 692 observed, 716.16 expected, observed/expected ratio (o/e) 0.97, 90% interval 0.91 to 1.03.
Homologues: Orthologues: chimpanzee FRMPD1 (99% identical), macaque FRMPD1 (97% identical), dog FRMPD1 (84% identical), pig FRMPD1 (82% identical), guinea pig FRMPD1 (79% identical), rabbit FRMPD1 (78% identical), mouse Frmpd1 (77% identical), rat Frmpd1 (75% identical), tropical clawed frog frmpd1 (44% identical), Drosophila melanogaster CG42788 (19% identical), Caenorhabditis elegans frm-8 (13% identical), zebrafish frmpd1a (12% identical). Paralogues in human: FRMPD4 (25% identical), FRMPD3 (21% identical).
Diseases named in the same sentence as FRMPD1 in open-access papers:
FRMPD1 is named in the same sentence as 5 diseases in open-access papers, as found by Europe PMC text mining. Sharing a sentence is not in itself a finding about the gene and the disease. The quoted sentences say what the papers report.
lung carcinoma (1 paper, 2025). "FRMPD1 epitomizes context-dependent oncoprotein regulation, exhibiting tumor-suppressive Hippo pathway activation in lung cancer versus pro-proliferative activity in HCC." (PMID 40699790, 2025). "Intriguingly, FRMPD1 demonstrates tissue-specific functional duality: it suppresses lung cancer via Hippo pathway activation yet drives HCC proliferation, highlighting the complexity of cancer signaling plasticity and metabolic reprogramming across tissue microenvironments." (PMID 40699790, 2025).
cancer (2 papers, 2020 to 2025). A tumor composed of atypical neoplastic, often pleomorphic cells that invade other tissues. "Searching for our mutated genes in the large pediatric cancer databases PECAN and PedcBioPortal (any tumor) revealed CTNNB1 as the most commonly mutated gene, followed by DEPDC5 (several variants were identified in 12 types of pediatric tumors) in PECAN, and FRMPD1 in PedcBioPortal." (PMID 32432034, 2020).
tumor (2 papers, 2020 to 2025). "Diverging from canonical F-box protein functions in proteasomal substrate degradation, FBXO10 exhibits a non-degradative oncogenic mechanism in HCC by stabilizing FRMPD1 through K63-linked polyubiquitination—a functional dichotomy contrasting with its tumor-suppressive role in lymphoid malignancies." (PMID 40699790, 2025).
FRMPD1 also shares sentences with these, for which no sentence is quoted: breast carcinoma (1 paper); hepatoma (1).